AFP (alpha fetoprotein)
Diseases named in the same sentence as AFP in open-access papers (continued):
Sharing a sentence is not in itself a finding about the gene and the disease.
tumor (continued). "In addition, high serum AFP level has been identified as a biomarker for HCC associated with a more aggressive tumor phenotype and inferior outcomes after different treatment modalities in accordance with our statistical analyses." (PMID 36776366, 2022). "Alternatively, extracellular AFP has been reported to not only induce tumor cell proliferation via the AFP receptor but to also provoke the apoptosis of dendritic cells, causing the inhibition of the anti-tumor immune system." (PMID 35053580, 2022). "Cox multivariate regression analysis showed that age, white blood cell count, creatinine, total bilirubin, γ-GGT, LDH, tumor size ≥ 5 cm, tumor number ≥ 2, portal vein tumor thrombus, and AFP ≥ 400 ng/ml were independent risk factors for long-term survival in HCC." (PMID 35712507, 2022). "We believe that AFP progression could be associated with parameters related to the total tumor burden and tumor aggressiveness (pre-LT AFP levels, total tumor volume)." (PMID 35401038, 2022). "We then evaluated the clinical relevance of CPI, with the results of these analyses indicating no gender differences in CPI scores however, higher CPI scores were associated with significantly increased levels of AFP and were correlated with an advanced tumor status in HCC patients." (PMID 36408192, 2022). "Similarly, high ACLR was also associated with larger tumor size (P < 0.001), higher Edmondson’s grade (P < 0.001), vascular invasion (P < 0.001), higher AFP level (P = 0.038), advanced AJCC stage (P < 0.001), BCLC stage (P < 0.001), and CNLC stage (P < 0.001)." (PMID 35756674, 2022). "In the current study, we collected registry information for small HCC from the SEER database, and the multivariate analysis revealed that tumor size, histological grade, N stage, and AFP level were independent risk factors for extrahepatic metastasis in small HCC." (PMID 36127436, 2022). "Furthermore, increased STMN1 expression was linked to HCC patients’ age, gender, AFP level, tumor status, clinical stage, and histological grade." (PMID 36127700, 2022). "As expected, AFP ≥ 50 ng/mL prior to LDT was associated with tumor response (P < 0.001)." (PMID 34689234, 2022). "Moreover, we reported that decreased expression of GHR was significantly associated with serum AFP level>100 ng/ml (p = 0.048), increased tumor size (p = 0.02), vascular invasion (p = 0.002), and advanced pathological stage (p = 0.01)." (PMID 36374927, 2022). "Finally, the parameter of AFP SCORE progression can be integrated into a new predictive score for identifying the risk of tumor recurrence." (PMID 35401038, 2022). "In addition, high RPL22L1 expression was positively associated with poorly differentiated grade, large tumor size and high serum AFP level." (PMID 35973992, 2022). "The patients treated in Vietnam had a significant tumor recurrent rate after resection by multivariate analysis, in addition to other common risk factors, including male gender, higher AFP, larger tumor size, multiple tumors, macrovascular invasion and extrahepatic metastasis." (PMID 36423180, 2022). "For AFP levels below 1,000 ng/ml, the overall risk is determined by the tumor burden." (PMID 35529597, 2022). "Also decreased hepatic expression of GHR was associated with increased serum levels of AFP, large tumor size, vascular invasion, advanced histo-pathological stage, and worse outcome." (PMID 36374927, 2022). "Therefore, we conducted a genome-wide association study on 8 serum tumor markers (AFP, CA125, CA19-9, CA153, CA50, CEA, f-PSA, SCC-Ag) in the Han population from southern China." (PMID 35144566, 2022). "Moreover, HCC patients with high histological grade, high T stage, residual tumour, high pathological stage, vascular invasion, and AFP > 400 had higher risk scores; these characteristics often indicate that the disease is more serious in HCC patients." (PMID 35513781, 2022).
tumor (continued). "In addition to surgical approach, the current study revealed that tumor rupture, larger tumor, AFP > 200 ng/mL, and major complications also predisposed to the development of significant muscle loss." (PMID 36464698, 2022). "By using an AFP cut-off of 200 ng/ml they were able to define groups with a low (AFP <200 ng/ml and PET-), intermediate (PET+ or AFP >200 ng/ml), and high risk (PET+ and AFP >200 ng/ml) for tumor recurrence, leading to 5-year disease-free survival rates of 86.1%, 79.0%, and 18.5%, respectively." (PMID 35529597, 2022). "These include associations between TAD with tumor response, AFP response, and OS." (PMID 35394152, 2022). "LIHC is commonly associated with AFP, a diagnostic tumor marker." (PMID 36238495, 2022). "Our results also illustrated that tumor size, AFP ≥20 ng/ml and peripheral washout may indicate a higher risk of the MVI of the PLC." (PMID 35847955, 2022). "After multivariate logistic regression analysis, the significant risk factors, including AFP ≥ 400 kU/L (OR 0.072, P < 0.001), tumor diameter (TD) ≥ 5 cm (OR 0.400, P = 0.041), and TNM stage III–IV (OR 0.094, P < 0.001), were selected to construct a logistic regression model." (PMID 36180867, 2022). "Furthermore, AFP levels and the sum of the tumour diameter and number were significantly associated with HCC-specific death and this combination performed better than any other transplant criteria for HCC." (PMID 35740638, 2022). "Likewise, larger tumor size, more tumors, and higher AFP level have also been documented as risk factors for HCC prognosis." (PMID 35814378, 2022). "Furthermore, lower expression of STAT5 was significantly associated with serum AFP > 100 ng/ml, vascular invasion, advanced tumor stage, and poor patient prognosis." (PMID 36374927, 2022). "Pretreatment plasma cfDNA levels were weakly associated with AFP levels and maximal tumor size." (PMID 35884434, 2022). "In summary, MUC1-rs4072037 is significantly genome-wide associated with CA153 level (p = 1.28E-18) and 30 genetic loci were suggestively genome-wide associated with level of tumor markers (AFP, CA50, CA125, CA153, CA19-9, CEA, f-PSA, SCC-Ag) among the Han population from Southern China." (PMID 35144566, 2022). "Like platelet count and mean volume, the circulating tumor-associated markers like AFP, CEA, PSA, CA19-9 and CA72-4 might be limited to the aid diagnosis currently, because they are not sensitive or specific and not recommended for population screening." (PMID 36185270, 2022). "Nevertheless, it is well known that AFP may play an important prognostic role in the follow-up of these patients, as high AFP levels may signal more aggressive, multifocal tumours associated with venous portal thrombosis and/or metastasis." (PMID 36819823, 2022). "In addition to CSS, our research revealed that tumor size, tumor number, AFP level, and macrovascular invasion were independent risk factors associated with both RFS and OS by the multivariate Cox regression analysis." (PMID 35637856, 2022). "Our Clin_model detected tumor size and AFP as independent risk factors for the prediction model." (PMID 35664790, 2022). "In addition to imaging tests, serum markers such as alpha-fetoprotein (AFP) that is linked to the evolutionary stage of the tumor, have been used for diagnosis and prognosis of HCC." (PMID 36518850, 2022). "Aside from ICIs, new therapeutic approaches target tumor-specific antigens (TSA: antigens only expressed by tumor cells) and tumor-associated antigens (TAA: antigens overexpressed by tumor cells but also expressed by healthy cells) such as glypican-3 (GPC3) or alpha-fetoprotein (AFP)." (PMID 36139683, 2022). "We evaluated the clinicopathological characteristics of the FOXM1-high and -low HCC cases, and FOXM1-high HCC was significantly associated with high serum AFP levels, poorly differentiated histological findings, large tumor size, and a high frequency of microscopic portal vein invasion." (PMID 35955438, 2022).
tumor (continued). "AFP is a promising tumor-associated antigen target for the generation of DC-based vaccines." (PMID 35619702, 2022). "Patients with a high risk for waitlist dropout had AFP ≥500 ng/mL and accelerated tumour progression, and are those who may rather benefit from early locoregional therapy." (PMID 35637985, 2022). "Additionally, AFP is a frequently used biomarker in screening for HCC associated with tumor aggressiveness since it is produced during times of sustained liver injury and regeneration." (PMID 35865863, 2022). "Recent research has shown that the combined assay of AFP with other tumor markers might potentiate the diagnostic efficiency." (PMID 35711497, 2022). "We found that male, multiple tumors, low albumin, high AST, high γ-GT, and high viral load were associated with positive AFP, suggesting that patients with positive AFP may tend to have poorer liver function and higher tumor aggressiveness." (PMID 34976804, 2021). "The model to predict tumor recurrence after LDLT (MoRAL) score using AFP and PIVKA-II might also be used to evaluate high-risk patients for tumor recurrence after RFA." (PMID 34638613, 2021). "The clinical pathologic study revealed PGC7 positive staining correlates with poor survival outcome in HCC patients and was significantly associated with advanced tumor stage (Pearson χ2 test, P < 0.05) and relatively high AFP level (Pearson χ2 test, P < 0.05)." (PMID 33500560, 2021). "Interestingly, we found that the expression of ACTN1 was closely associated with alpha-fetoprotein level, tumor thrombus, tumor size and TNM stage." (PMID 33413564, 2021). "Serum AFP level and tumor number represent two consensus biomarkers associated with HCC recurrence." (PMID 34094938, 2021). "Furthermore, high expression levels of LRB1 were detected in a cohort of 326 HCC-related patients and positively associated with clinical features (AFP expression), large tumor sizes, and tumor stage." (PMID 34206504, 2021). "For OS, univariate analysis showed that narrow tumor margin, high recurrent AFP level, larger recurrent tumor size, and early recurrence showed association with shorter OS (all P < 0.05), while initial AFP level, tumor margin, MVI, and TTR were shown to be as independent risk factors of OS." (PMID 34127007, 2021). "Thus, it’s necessary to find and validate other serum tumor markers that in association for AFP would increase the sensitivity and the specificity in the HCC diagnosis." (PMID 33971914, 2021). "In addition to AGLR, AFP, tumor size, TNM stage, MVI and recurrence were also associated with a shorter OS for HCC patients." (PMID 33536005, 2021). "However, elevated PLR values are not highly associated with vascular invasion, tumor numbers, AFP levels or poor tumor grades." (PMID 34535132, 2021). "In multivariate Cox regression analysis, incomplete response (P<0.001) and Child-Pugh class B (P=0.017) were independent risk factors for tumor progression, while higher AFP level (P=0.011) and Child-Pugh class B (P=0.026) were independent risk factors for poor OS." (PMID 34733792, 2021). "As a result, preventing HCC recurrence after LT remains an important issue, and many risk factors associated with tumor recurrence have been identified, such as tumor behavior, differentiation type, alpha-fetoprotein (AFP) level, and serum neutrophil-to-lymphocyte ratio." (PMID 34898547, 2021). "Furthermore, the association between RFS and Ki67, size, tumor number, AFP, MVI, and BIS score was analyzed using multivariate regression analyses, wherein Ki67, size, MVI, and BIS were found to be independent prognostic predictors of RFS." (PMID 35004275, 2021). "Moreover, PVTT is clinically associated with large tumor size, increased tumor number, higher tumor grade, worse Child–Pugh class, and higher serum alpha-fetoprotein (AFP)." (PMID 34344378, 2021).
tumor (continued). "The high expression of MUC1 was significantly associated with the level of CA19-9 (P < 0.05), AFP (P < 0.05), and more aggressive tumor phenotypes including larger tumor size (P < 0.05), presence of lymph node metastases (P <0.05), vascular infiltration (P < 0.05), and advanced TNM stage (P < 0.05)." (PMID 34729096, 2021). "Moreover, our analysis of risk factors of tumor recurrence showed that exceeding the AFP score was dynamic." (PMID 34069594, 2021). "Moreover, high EpCAM expression was associated with positive AFP expression (P = 0.042), vascular invasion rate (P = 0.043), poor tumor differentiation (P = 0.020), and advanced tumor–node–metastasis stage (P = 0.002)." (PMID 31740785, 2020). "In patients at intermediate stages, AFP has been associated with tumor progression in patients listed for LT who underwent tumor bridging therapies while on the waiting list or in patients who received locoregional tumor treatment to reduce their tumor burden." (PMID 32492896, 2020). "Also, it was found that tumor burden and serum level of AFP are well-established markers associated with HCC recurrence." (PMID 32426129, 2020). "Therefore, we stratified patients by low or high risk score and found the following factors to influence risk: AFP, new tumor event and cancer status." (PMID 32592379, 2020). "Higher serum AFP level was associated with higher tumor grade (Chi-square: 8.07, P = 0.018)." (PMID 31897235, 2020). "It is noted however that there were only 8 patients with BCLC 0 and A with large single tumours, on which performance of AFP was performed, which could account for some diagnostic bias." (PMID 33357229, 2020). "AFP is an established tumor marker for HCC and may be associated with the prognosis of HCC patients." (PMID 32280757, 2020). "In the multivariate analysis, independent risk factors for tumor recurrence were AFP/TTV > 2 (HR = 1.62, 95% CI = 1.29–1.98, P = 0.042), Macrovascular invasion (HR = 2.03, 95% CI = 2.17–2.38, P = 0.021, and microvascular invasion (HR = 1.36, 95% CI = 1.08–1.77, P = 0.019)." (PMID 32426129, 2020). "Furthermore, greater tumour size at baseline was significantly associated with higher serum AFP ≥ 200 ng/ml following initial TACE which was one of the key prognostic determinants associated with lower OS on multivariate analysis." (PMID 32471447, 2020). "NF90-Ser382 phosphorylation was positively associated with tumor size and AFP level." (PMID 32123579, 2020). "In our study, neutrophil count was associated with tumor size, vascular invasion, extrahepatic metastasis, and AFP level, which suggest that increased neutrophil counts alter the tumor microenvironment and the formation of the inflammatory microenvironment thus promoting tumor growth and metastasis." (PMID 32993594, 2020). "Most of the series identified that larger TTV had more tumor burden with associated larger tumor size and number, high AFP level, macrovascular invasion, and advanced tumor stages with the consequent shorter OS than others with smaller TTV, as seen also in our study." (PMID 32368340, 2020). "In this work, Shachaf and colleagues demonstrated that Myc overexpression specifically in the liver induces HCC development in animals while Myc inactivation results in tumor cells differentiating into hepatocytes and biliary epithelial cells and a rapid loss of AFP." (PMID 31979130, 2020). "AFP level (≥400 vs. <400 ng/mL) and tumor size (≥5 vs. <5 cm) were risk factors for PFS." (PMID 33521054, 2020). "Additionally, the level of AFP and larger tumor size were found significantly associated with higher expression of OCT4 (P<0.05)." (PMID 32373219, 2020). "MiR-301 levels were significantly linked with tumor size and serum alpha-fetoprotein (AFP)." (PMID 33260407, 2020).
tumor (continued). "For that population, the number of PRBC units transfused during surgery and the preoperative AFP serum levels were associated with decreased overall survival, whereas the presence of tumor microvascular invasion was the single most important predictor of HCC recurrence." (PMID 33134370, 2020). "Furthermore, AC092171.4 expression was significantly associated with age (p=0.048), α-fetoprotein (AFP) levels (p<0.001), tumor size (p<0.001), the number of tumor nodules (p=0.007), and the presence of cancer emboli (p=0.005)." (PMID 32692718, 2020). "Alpha-fetoprotein (AFP) is a fetal glycoprotein associated with tumor." (PMID 31516840, 2019). "An unsatisfactory decrease in AFP level during tumor treatment may be caused by residual diseases or acquired chemotherapy resistance." (PMID 31836006, 2019). "Considering the prognostic and predictive capabilities of AFP in HCC, our hypothesis is that the molecular profile of high AFP tumours differs from those with low AFP and might be associated with VEGF signalling." (PMID 31285588, 2019). "Studies suggested that a lectin-reactive AFP form indicated a high risk of tumour recurrence." (PMID 31652641, 2019). "In addition, higher Tregs infiltrations are associated with multiple liver tumours, high AFP levels, poor tumour differentiation, and advanced stage and vascular invasion, and are therefore a measure of poor prognosis." (PMID 30893948, 2019). "In addition to being a diagnostic serum tumor marker, AFP was reported to have functional roles in HCC." (PMID 31635078, 2019). "Similar to our study, previous risk models have attempted to employ pre-LT AFP, largest tumor diameter and the number of nodules to predict the post-LT HCC recurrence, but the characteristics of their study population (western participants with predominantly HCV) was different." (PMID 31752756, 2019). "The primary tumor size, serum AFP, and serum albumin were significantly associated with mortality." (PMID 31232945, 2019). "As expected, no other demographic considered in the study, either in clinical or laboratory data, including Milan criteria (P = 0.149), tumor location (P = 0.798) and AFP levels (P = 0.444), were significantly associated with near-complete necrosis at the P < 0.05 level." (PMID 31690274, 2019). "Patients in Cluster2 were younger (mean age 49.39 vs. 52.30 years old, p = 0.037), had a higher predicted risk for metastasis (84.3% vs. 15.7%, p < 0.0001), higher AFP level (p < 0.0001), bigger tumor size (p = 0.019), and higher proportion of patients with a higher tumor grade." (PMID 31847435, 2019). "Moreover, high expression of DEPTOR was associated with high serum AFP levels, increased tumor size, vascular invasion and more advanced TMN and BCLC stage." (PMID 31228948, 2019). "And elder age (≥ 60 years), male, Black or American Indian/Alaska native ethnicity, unmarried status, poorly or undifferentiated pathology grade, positive AFP, large tumor size (≥ 2 cm) were regarded as risk factors for poor survival with significant difference (All P < 0.05)." (PMID 30445928, 2018). "With the genetic correction, higher odds ratios (ORs) for digestive cancer risk were found for the genetic corrected levels of tumor biomarkers compared with their raw serum levels (1.57 vs. 1.65 for AFP; 1.19 vs. 1.21 for CA19–9; 1.09 vs. 1.10 for CEA, respectively)." (PMID 29484118, 2018). "Similarly, the poor prognosis group of 5-gene score showed shorter DSS (p = 0.045) and early RFS (p = 0.023) as well as a significant association with microvascular invasion, tumor size (> 5 cm), elevated AFP levels, and RB1 mutations." (PMID 29776391, 2018). "Because high tumor DNA-PKcs expression was closely associated with elevated serum AFP levels, presence of portal vein invasion and large tumor sizes (>3.0 cm), staining of the nuclei at the tumor edge appears to be associated with tumor progression and growth in HCC tumors." (PMID 30301934, 2018).